H3C1 (H3 clustered histone 1)
Description:
Core component of nucleosome. Nucleosomes wrap and compact DNA into chromatin, limiting DNA accessibility to the cellular machineries which require DNA as a template. Histones thereby play a central role in transcription regulation, DNA repair, DNA replication and chromosomal stability. DNA accessibility is regulated via a complex set of post-translational modifications of histones, also called histone code, and nucleosome remodeling.
Synonyms: H3FA; HIST1H3A; H3/A
Gene: Protein-coding gene on chromosome 6 (26,020,451 to 26,021,487, forward strand). Ensembl gene ENSG00000275714.
Subcellular location: Nucleus; Chromosome
Subcellular location (Human Protein Atlas): Nucleoplasm
Pathways (Reactome):
Gene expression (Transcription): B-WICH complex positively regulates rRNA expression; DNA methylation; ERCC6 (CSB) and EHMT2 (G9a) positively regulate rRNA expression; MLL4 and MLL3 complexes regulate expression of PPARG target genes in adipogenesis and hepatic steatosis; NoRC negatively regulates rRNA expression; PRC2 methylates histones and DNA; RNA Polymerase I Promoter Escape; RNA Polymerase I Promoter Opening; RUNX1 regulates genes involved in megakaryocyte differentiation and platelet function; RUNX1 regulates transcription of genes involved in differentiation of HSCs; Regulation of endogenous retroelements by KRAB-ZFP proteins; Regulation of endogenous retroelements by Piwi-interacting RNAs (piRNAs); Regulation of endogenous retroelements by the Human Silencing Hub (HUSH) complex; SIRT1 negatively regulates rRNA expression; Transcriptional regulation by small RNAs
Chromatin organization: CHD1 and CHD2 subfamily; CHD6, CHD7, CHD8, CHD9 subfamily; ChAHP complex assembly; Chromatin modifying enzymes; HATs acetylate histones; HDACs deacetylate histones; HDMs demethylate histones; Interaction of NuRD complexes with transcription factors; NuRD complex assembly; PKMTs methylate histone lysines; RMTs methylate histone arginines
Disease: Defective pyroptosis; Dengue Virus-Host Interactions; HCMV Early Events; HCMV Late Events
Signal Transduction: Activated PKN1 stimulates transcription of AR (androgen receptor) regulated genes KLK2 and KLK3; Estrogen-dependent gene expression; Formation of the beta-catenin:TCF transactivating complex; Pre-NOTCH Transcription and Translation
Developmental Biology: Activation of anterior HOX genes in hindbrain development during early embryogenesis; Chromatin modifications during the maternal to zygotic transition (MZT); Transcriptional regulation of granulopoiesis
Immune System: FXIIa activates plasma kallikrein-kinin system; Interleukin-7 signaling; Regulation of PD-L1(CD274) transcription
and 8 more pathways
Gene Ontology:
Molecular function: cadherin binding; protein binding; structural constituent of chromatin; nucleosomal DNA binding; DNA binding; protein heterodimerization activity
Biological process: epigenetic regulation of gene expression; nucleosome assembly; chromatin organization; heterochromatin formation; telomere organization
Cellular component: chromatin; extracellular exosome; membrane; nucleoplasm; nucleosome; nucleus; protein-containing complex; extracellular region; chromosome
Genetic constraint (gnomAD): Loss-of-function variants: 14 observed, 7.82 expected, observed/expected ratio (o/e) 1.79, 90% interval 1.1 to 1.96. That is too few expected variants to judge how well the gene tolerates losing a copy. Missense variants: 326 observed, 208.19 expected, observed/expected ratio (o/e) 1.57, 90% interval 1.43 to 1.72. Synonymous variants: 181 observed, 80.83 expected, observed/expected ratio (o/e) 2.24.
Homologues: Orthologues: chimpanzee H3C3 (100% identical), dog H3C8 (100% identical), macaque H3C12 (100% identical), mouse H3c1 (100% identical), Drosophila melanogaster His3:CG33812 (99% identical), zebrafish si:ch1073-153i20.2 (99% identical), zebrafish si:ch211-113a14.20 (99% identical), zebrafish si:ch211-113a14.23 (99% identical), zebrafish si:ch211-113a14.27 (99% identical), zebrafish zgc:173552 (99% identical), Caenorhabditis elegans his-17 (97% identical), Caenorhabditis elegans his-2 (97% identical), and 9 more. Paralogues in human: H3C10 (100% identical), H3C11 (100% identical), H3C12 (100% identical), H3C2 (100% identical), H3C3 (100% identical), H3C4 (100% identical), H3C6 (100% identical), H3C7 (100% identical), H3C8 (100% identical), H3C13 (99% identical), H3C14 (99% identical), H3C15 (99% identical), and 8 more.
Diseases named in the same sentence as H3C1 in open-access papers:
H3C1 is named in the same sentence as 7 diseases in open-access papers, as found by Europe PMC text mining. Sharing a sentence is not in itself a finding about the gene and the disease. The quoted sentences say what the papers report.
alcoholism (1 paper, 2021). "Estrogen signaling pathway was detected and proteins H3C1, H3C13, H3C15 were associated with pathways such as alcoholism, histone modifications, systemic lupus erythematosus." (PMID 33692444, 2021).
H3C1 also shares sentences with these, for which no sentence is quoted: tumor (2 papers); Arthritis (1); mental retardation (1); systemic lupus erythematosus (1); uterine corpus endometrial carcinoma (1); α-thalassemia (1).